ENSG00000285641 (novel protein)
Gene: Protein-coding gene on chromosome 1 (153,975,850 to 153,986,246, reverse strand). Ensembl gene ENSG00000285641.
Genetic constraint (gnomAD): Missense variants: 186 observed, 264.81 expected, observed/expected ratio (o/e) 0.7, 90% interval 0.62 to 0.79. Synonymous variants: 82 observed, 94.88 expected, observed/expected ratio (o/e) 0.86, 90% interval 0.72 to 1.04.